TF (transferrin)
Diseases named in the same sentence as TF in open-access papers (continued):
Sharing a sentence is not in itself a finding about the gene and the disease.
tumor (continued). "While non-antibody ligands, such as transferrin or folate, may be useful targeting agents for their specific receptors on tumor cells, the same ligands are also abundant in certain normal cells, thereby leading to unacceptably low tumor-to-normal tissue ratios and consequent cytotoxicity." (PMID 37760506, 2023). "Moreover, Se-PC PDT treatment may dilute tumor metabolism and proliferation by depressing the activity of the glucose transporter GLUT1 (gene Slc2a1) and the iron transport-related factors LCN2 (gene Lcn2) and transferrin (gene Trf), which reduce the synthesis of hemoglobin and inhibit ferroptosis." (PMID 37994159, 2023). "Transferrin, a negative APP, and lipoproteins, complement and immunoglobulins, mainly IgA or IgM are β GLOB; inflammation, neoplasia and various metabolic conditions show increased β GLOB." (PMID 34359253, 2021). "After identifying the differentially expressed genes (DEGs) in tumor and nontumor tissues, five kinds of analyses, namely, functional annotation, protein-protein interaction (PPI) network, hub gene selection, TF-miRNA-mRNA regulatory network analysis, and ferroptosis mechanism, were performed." (PMID 36247089, 2022). "They found tumour uptake of >10%ID/g at 24 and 48 h after administration of 89Zr-transferrin, also labelled using the iron-binding siderophore desferrioxamine (DFO) as a metal ion chelator rather than relying on the transferrin itself to bind to the 89Zr4+ ion." (PMID 30225616, 2018). "The aim of this study was to prepare the artemisinin and transferrin-loaded magnetic nanoliposomes in thermosensitive and non-thermosensitive forms and evaluate their antiproliferative activity against MCF-7 and MDA-MB-231 cells for better tumor-targeted therapy." (PMID 24887240, 2014).
cancer (533 papers, 2005 to 2026). A tumor composed of atypical neoplastic, often pleomorphic cells that invade other tissues. "High TF expression on tumor cells has been linked with cancer-associated thrombosis and metastatic progression." (PMID 40730678, 2025). "Tn and sTn antigens linked to cancer have been identified in both the larval and adult stages of E.granulosus, as well as TF antigens linked to CRC." (PMID 40297577, 2025). "Our observations build upon previous research linking TF-positive EVs to cancer-associated thrombosis and cancer progression." (PMID 40312345, 2025). "Tumor - associated glycoproteins, such as sialyl - Tn, TF, and Tn, are often used in cancer diagnostics and prognosis and are mainly found on cancer cells." (PMID 40297577, 2025). "As a global regulator of protein expression, imbalance of TF expression is linked to the development of diseases, such as cancer." (PMID 38674385, 2024). "Compared to the strong binding to the TF-disaccharide, hRTL was only poorly bound to Tn (GalNAc) and sialyl-Tn (Siacα2-3GalNAc) antigens, which are also common cancer-specific mucin-associated glycans." (PMID 39330281, 2024). "The risk of cancer-related mortality increased as serum albumin, prealbumin and transferrin levels decreased." (PMID 38438901, 2024). "The present study reported that low albumin, prealbumin, and transferrin levels were associated with worse prognosis in patients with cancer cachexia." (PMID 38438901, 2024). "The present study, comprehensively assessed the association between albumin, prealbumin, and transferrin levels and prognosis in cancer cachexia patients for the first time." (PMID 38438901, 2024). "In line with our observations, hypoxia was shown to augment TF expression in ischemia-associated thrombosis and cancer." (PMID 38414067, 2024). "Because of this, many groups have developed diagnostic and therapeutic agents by binding to transferrin drugs or imaging agents to target cancer cells." (PMID 38117806, 2023). "For example, binding of galectin-3 to TF on cancer-associated transmembrane mucin protein MUC1 increases cancer cell heterotypic adhesion to vascular endothelium and promotes endothelial secretion of metastasis-promoting cytokines such as GM-CSF and IL-6." (PMID 37612278, 2023). "Of note, besides that of CP, expression of other metalloenzymes including TF, MT-1 and MT-2 is also increased in BM in the present study, all described to up-regulated by HIFs and associated to carcinogenesis and cancer treatment resistance." (PMID 38006431, 2023). "And hypoxic cancer cells were shown to release substantial amounts of TF that was mainly associated with secreted microvesicles with exosome-like characteristics." (PMID 36473847, 2022). "Improved gene and paclitaxel delivery to the cancer cells was reported with transferrin linked nanostructured lipid carriers." (PMID 36330493, 2022). "This different binding allows us to observe changes in the representation of various forms of transferrin associated directly or indirectly with cancer in a number of patients compared with cancer-free women." (PMID 36555993, 2022). "Approximately 90% of human cancer types and the majority of precancerous legions express the TF antigen, a truncated O-linked cell surface glycan that is only found on developmental cells and cancer cells." (PMID 34070233, 2021). "High levels of extracellular vesicle tissue factor (EV TF) activity have also been associated with poor prognosis in cancer patients." (PMID 33658563, 2021). "The risk of cancer occurrence and mortality in the group with above 60% transferrin saturation relative to the 0–30% group is 1.81 and 1.73." (PMID 34589492, 2021). "For people with transferrin saturation more than 43%, dietary iron more than 18 mg/day increases cancer risk." (PMID 34589492, 2021). "Various cancers contain TF at high concentrations; therefore, cancer-derived TF itself is also associated with Trousseau’s syndrome." (PMID 30959839, 2019).
cancer (continued). "They found that there was a significant association between RTPs' concentration and survival in cancer patients and among RTPs and prealbumin had the most correct prognosis rate with 91.9% compared to transferrin and retinol binding protein." (PMID 26904109, 2016). "Intriguingly, ELMER often identified a particular TF in the same cancer type or types where it is most frequently mutated." (PMID 25994056, 2015). "It has been documented that cancer cells need high iron levels to proliferate; hence cancer cells typically absorb a significantly larger amount of transferrin than normal cells and were more susceptible to artemisinin cytotoxicity." (PMID 24887240, 2014). "Among persons with increased transferrin saturation, a daily intake of dietary iron of more than 18 mg is associated with an increased risk of cancer." (PMID 24152754, 2013). "This study shows that the presence of galectin-3 at pathologically-relevant circulating galectin-3 concentrations increases cancer cell homotypic aggregation by interaction with cancer-associated MUC1 that expresses the TF disaccharide." (PMID 20565834, 2010). "The increased expression of MUC1 and the increased occurrence of TF antigen are both associated, independently, with high metastatic potential of the cancer cells and poor prognosis of the patients." (PMID 20565834, 2010). "Employing our established SPR-based liquid biopsy platform with only 10 μL of serum per assay, we found that exosomal TF-Ag-α exhibited exceptional diagnostic performance, achieving 99.2% sensitivity, 100% specificity, and an AUC of 0.999 for distinguishing cancer patients from controls." (PMID 41374931, 2025). "TF expression can be an indicator for cancer risk prediction and cancer subtyping." (PMID 40256837, 2025). "Likewise, other studies found a positive associated between cancer risk in a variety of tissues and transferrin saturation." (PMID 38732562, 2024). "Also, studies involving cancer and TFs resulted in anti-conservative or uniform p-value distributions with similar probabilities to non-cancer/non-TF studies (risk ratios with 95% CI are 0.95 (0.83; 1.07) and 0.99 (0.74; 1.28), respectively)." (PMID 36862747, 2023). "Thus, hJAA-F11 antibodies, the humanized versions of the murine monoclonal IgG3 antibody mJAA-F11, hold promise towards targeting TF-Ag-α expressing cancers for therapeutic and diagnostic applications." (PMID 36264086, 2022). "In addition, rhodamine-labeled transferrin-modified liposomes demonstrated higher association with cancer cells compared to human astrocytes, with significant internalization in cancer cells compared to non-targeted liposomes." (PMID 32290224, 2020). "As natural antibodies against TF are produced from the body, the risk within such a vaccination for cancer patient is relatively small, so that it could be a rather promising therapeutic target." (PMID 26528431, 2015). "Systematic analysis of potential TF/Dnmt interaction revealed by in vitro studies may also reveal new specific interactions implicated in apoptosis resistance in cancer cells." (PMID 24709797, 2013). "Longer LOS was associated with cancer, transferrin, IL-6 and albumin (p < 0.05)." (PMID 17505683, 2007). "TF genes serve as regulators for the gene expression that may cause the generation of cancer cells." (PMID 39432502, 2024). "In a cohort of patients first visited for UADT cancers, we estimated their alcohol consumption by measuring Ethyl Glucuronide/EtG (a long-lasting metabolite of ethanol) in the hair and carbohydrate-deficient transferrin/CDT (short-term index of alcohol intake) in the serum." (PMID 37371963, 2023). "Targeting this hemostasis-cancer axis-via TF inhibition, anticoagulation, or antiplatelet therapy-offers therapeutic promise to disrupt proliferation, immune escape, and metastasis." (PMID 42086829, 2026).
cancer (continued). "Transferrin-conjugated LPHNPs improved their entrapment, sustained release, targeted uptake, and antiproliferative activity, making them a promising cancer therapy approach." (PMID 41471261, 2025). "This exosomal TF-Ag-α–based assay holds strong potential to complement existing tests, facilitate cancer screening and early detection, and ultimately improve patient outcomes." (PMID 41374931, 2025). "A previous study has successfully identified TfR1-specificpeptides on cancer cells via phage display; these peptides bind asite distinct from endogenous transferrin, thus avoiding competitiveinhibition and exhibiting cellular internalization." (PMID 41476540, 2025). "Prebiotic intake in perioperative CRC patients improved serum immunologic indicators (IgG, transferrin), suggesting GM modulation can support immune function during cancer treatment." (PMID 41561086, 2025). "Alternative ligands such as transferrin, aptamers, and antibodies were investigated for cancer-targeted drug delivery beyond the folate and RGD system." (PMID 41471261, 2025). "This is consistent with reports showing dynamic TF expression in other cancers, such as non-small-cell lung cancer (NSCLC)." (PMID 40806559, 2025). "Transferrin-modified cancer cell membrane-coated HB nanocrystals have been developed for targeted cancer therapy." (PMID 40362277, 2025). "This direct inhibition of TF‐FVIIa activity resulted in reduced cancer cell proliferation, indicating potential anti‐tumoral effects of apixaban." (PMID 40292918, 2025). "Elevated levels of ferritin and transferrin saturation have been correlated with poorer prognoses in various cancers, emphasizing the role of iron-thiol in cancer biology." (PMID 40675856, 2025). "TWIST, a transcription factor: TF protein that promotes cancer cell migration and metastasis, expression was significantly reduced in both hAME and DOX groups but remained unchanged with D + E treatment." (PMID 40537738, 2025). "For example, a large amount of transferrin (Tf) on the surface of cancer cells can bind to transferrin receptors (TfR) naturally present on the surface of EVs." (PMID 40840553, 2025). "prepared folate and transferrin (due to the high expression of their receptors in cancer cells) to co‐modify liposome delivery systems containing CGs." (PMID 40985476, 2025). "For instance, dihydroartemisinin complexes with transferrin effectively inhibit cancer cell proliferation while sparing normal cells." (PMID 40943352, 2025). "Incorporating transferrin into drug delivery systems has been shown to enhance cytotoxic effects in drug-sensitive cancer cells, offering a potential method to surpass the limitations of current cancer therapies." (PMID 40144390, 2025). "These networks include common networks (e.g., PPI, co-pathway network, and TF-target network) and cancer specific networks (e.g., co-expression network, co-methylation network, co-mutation network, ceRNA network, and gene dependency network)." (PMID 39186807, 2024). "GBM cancer stem-like cells demonstrate increased expression of iron uptake proteins transferrin (TF) and transferrin receptor (TFRC), as well as the iron storage protein ferritin." (PMID 38239626, 2024). "Essentially, Ru ions can bind to transferrin proteins, which accordingly bind to transferrin receptors that are highly expressed on cancer cells." (PMID 39409175, 2024). "MYC-positive cancer can also be detected through real-time transferrin-based PET (Positron Emission Tomography) scans that utilize Gallium-68 Citrate." (PMID 38674385, 2024). "TF expression enhances cancer progression and metastasis, not only via coagulation and platelet activation but also by TF activation of protease activated receptor-2 (PAR-2) signalling." (PMID 39105809, 2024). "The optimal cutoff value of albumin, prealbumin, and transferrin for cancer cachexia patients in our study was 38.7 g/L, 0.17 g/L, and 2.29 g/L, respectively, as calculated by standardized log-rank statistics." (PMID 38438901, 2024).
cancer (continued). "In cancer, TF expression is regulated by both specific oncogenes and environmental factors and shown to regulate primary growth and metastasis formation in a variety of cancer models." (PMID 38066386, 2024). "Owing to the overexpression of receptors for folic acid (FA), hyaluronic acid (HA), transferrin (Tf), and biotin on cancer cells, these entities are most often used to decorate tumor-targeting QDs." (PMID 39269086, 2024). "Hepatic proteins, including albumin, prealbumin, and transferrin have been confirmed to be prognostic predictors in various cancers." (PMID 38438901, 2024). "Protoparvovirus H-1PV targets cancer cells by exploiting overexpressed receptors like the transferrin and Heparan sulphate proteoglycan receptors, making them more susceptible to infection than non-cancerous cells." (PMID 38576614, 2024). "It has been proven that Mn(II) cations are mainly absorbed and transported by transferrin (Tf) and the transferrin receptor (TfR) system, which is highly expressed in cancer cells." (PMID 38398576, 2024). "TfR is a membrane receptor that binds to transferrin, the main iron-carrying protein, to regulate the amount of iron that enters the cell, which is a high requirement for the proliferation of cancer cells." (PMID 39061185, 2024). "Accumulating studies have also confirmed that prealbumin and transferrin were effective for survival prediction in patients with cancer, even with a better performance than albumin." (PMID 38438901, 2024). "Low albumin, prealbumin, and transferrin levels were all independent prognostic factors affecting patients with cancer cachexia, especially in patients in the advanced stages." (PMID 38438901, 2024). "This encapsulation yielded PS⸦M1 and PS⸦M2 host–guest systems, which can be internalized into cancer cells after the Ru-transferrin-mediated binding to transferrin receptors." (PMID 39409175, 2024). "Transferrin is a membrane protein with a high expression in various cancer cells such as the brain, breast, and lung." (PMID 38816723, 2024). "It has been reported that the milk protein lactoferrin works to prevent cancer progression through iron chelation by competing with transferrin, which is in the same family of proteins." (PMID 38595825, 2024). "Although iron metabolism has been reported closely related to cancer progression, the role of TF in cancer has yet to be investigated." (PMID 39606245, 2024). "Because TF has a high affinity with the TFR1 membrane receptor, which is often overexpressed in cancer cells, transferrin is an excellent binding partner for chemotherapy." (PMID 38816377, 2024). "Transferrin (Tf) receptors are upregulated on the surfaces of cancer cells, which makes them potential targets for targeting ligands." (PMID 38399237, 2024). "Their results showed that the transferrin improved the blood–brain barrier crossing, cell uptake, and toxicity of cancer cells (229% more than Taxotere)." (PMID 38816723, 2024). "This platform was covered with a cancer-focusing substance called transferrin (Tf) and labeled with a radioactive element (89Zr) to specifically target the bone marrow." (PMID 39128942, 2024). "FOXM1 is a spatiotemporally expressed master TF activated by aberrant KRAS signaling to drive cancer initiation, self-renewal, and proliferation." (PMID 37191407, 2023). "Due to its TF specificity, jacalin is considered a promising drug-delivery molecule to target cancer cells." (PMID 38139227, 2023). "In the future, we plan to conjugate the AuNP with a cancer cell specific structure (such as transferrin, folate, or antibody) to provide vector for targeted intracellular delivery." (PMID 37674013, 2023). "This study aimed to explore the potential of novel hybrid lipid nanoparticles, composed of biocompatible zein and conjugated to the cancer-targeting ligand transferrin." (PMID 38004621, 2023).